HLA-DPB1 (major histocompatibility complex, class II, DP beta 1)
Diseases named in the same sentence as HLA-DPB1 in open-access papers (continued):
Sharing a sentence is not in itself a finding about the gene and the disease.
pulmonary arterial hypertension (4 papers, 2012 to 2019). Pulmonary arterial hypertension (PAH) is a group of diseases characterized by mean pulmonary artery pressure >20 mmHg and elevated pulmonary arterial resistance leading to right heart failure. "The mechanism of rs2856830 involvement in pulmonary arterial hypertension is probably through its association with specific HLA-DPB1 alleles." (PMID 30527956, 2019). "We found that the pulmonary arterial hypertension-enriched C allele of rs2856830 was associated with HLA-DPB1*02:01/02:02/16:01 (all p<1 × 10–9 after false discovery rate correction), which all contain the Glu69 residue." (PMID 30527956, 2019). "We report that HLA-DPB1 alleles are associated with pulmonary arterial hypertension and have a pivotal role in determining disease progression." (PMID 30527956, 2019). "The specific variant discovered was located in HLA-DPB1 and,surprisingly, correlated with two seemingly opposite outcomes: increased risk for thedevelopment of pulmonary arterial hypertension, but improved survival once havingdeveloped pulmonary arterial hypertension." (PMID 30527955, 2019). "HLA-DPB1, and wider immune regulatory pathways, should be considered a priority for patient stratification and investigation of new treatments in pulmonary arterial hypertension." (PMID 30527956, 2019). "In more detail, HLA-DPB1 is a known COPD gene related to disease severity, SERPINA6 was associated with emphysema, a deletion in ADORA2B was shown to be associated with a decrease in lung fibrosis and pulmonary hypertension, and ELMOD2 is a candidate gene for familial idiopathic pulmonary fibrosis." (PMID 30845926, 2019).
Achalasia (3 papers, 2023 to 2024). A disorder of esophageal motility characterized by the inability of the lower esophageal sphincter to relax during swallowing and by inadequate or lacking peristalsis in the lower half of the body of the esophagus. "Whole-exome sequencing (WES) on achalasia patients and controls revealed an association between the disease and common missense variants rs1705003 (CUTA) and rs1126511 (HLA-DPB1), and three rare variants (CREB5, ESYT3, and LPIN1) in an independent cohort." (PMID 38792545, 2024). "Thirteen genes associated with risk alleles of achalasia exhibited differential expression in C1QC+ macrophages, including CUTA and HLA-DQB1, compared with 18 risk genes that overlapped with DEGs in TRM, including HLA-DRB1 and HLA-DPB1." (PMID 37542039, 2023).
acute myeloid leukemia (3 papers, 2024 to 2026). Acute myeloid leukemia (AML) is a group of neoplasms arising from precursor cells committed to the myeloid cell-line differentiation. "Among these alleles, the existing literature highlights associations between aplastic anemia and HLA-B*49:01:01, acute myeloid leukemia and HLA-C*07 and childhood common acute lymphoblastic leukemia and HLA-DPB1*02:01." (PMID 39329950, 2024).
colon carcinoma (3 papers, 2019 to 2025). "Previous studies have shown that HLA-DPB1 is a susceptibility locus for colon cancer." (PMID 38877387, 2024).
Graves disease (3 papers, 2019 to 2022). Graves' disease is an autoimmune disorder that leads to overactivity of the thyroid gland (hyperthyroidism).It is caused by an abnormal immune system response that causes the thyroid gland to produce too much thyroid hormones. "In line with this speculation, HLA-DPB1*02:02 was associated with a better prognosis in another autoimmune condition—Graves’ disease in the Japanese population." (PMID 35661780, 2022).
Hodgkin's disease (3 papers, 1999 to 2024). "It has been suggested in a number of studies that susceptibility to adult Hodgkin's disease (HD) is influenced by the HLA class II region, and specifically by alleles at the HLA-DPB1 locus." (PMID 10424743, 1999). "Nonetheless, the literature also discusses the protective role of HLA-DQB1*05 against Hodgkin lymphoma, complemented by the protective effect conferred by HLA-DPB1*04:01 in this disease." (PMID 39329950, 2024). "In our study, genes related to major histocompatibility complex (MHC) class I and II machinery/biosynthesis such as HLA-DRA, CTSS, HLA-DPA1, HLA-DPB1, CTSC, B2M genes were expressed at higher levels in the mixed-cellularity subtype than in nodular sclerosis subtype at diagnosis." (PMID 36230815, 2022).
narcolepsy (3 papers, 2020 to 2023). A sleep disorder characterized by a tendency for excessive sleepiness during the day which occurs even after adequate sleep in the nighttime. "Therefore, the disease mechanism underlying the association of HLA-DPB1 with narcolepsy remains to be elucidated." (PMID 37380713, 2023).
ANCA associated vasculitis (2 papers, 2015 to 2025). "Among these, the prevalence of HLA-DPB1*0401 allele was higher in patients with PR3-ANCA associated vasculitis than in patients with MPO-ANCA associated vasculitis or healthy controls." (PMID 26223225, 2015).
autoimmune thyroid disease (2 papers, 2019 to 2023). Inflammatory disease of the thyroid gland due to autoimmune responses leading to lymphocytic infiltration of the gland. "HLA alleles (HLA-DPB1) and their variants (HLA-DPB1*02:02 and HLA-DPB1*05:01) have been described as contributors to the early pathogenesis of autoimmune thyroiditis." (PMID 36674671, 2023).
childhood asthma (2 papers, 2011 to 2026). "Then, we determined the HLA-DPB1 genotypes in 1135 cases and 2296 controls and found that DPB1*0901 was associated with pediatric asthma (P = 2.0×10−7, OR = 1.49)." (PMID 21814517, 2011).
endometriosis (2 papers, 2020 to 2025). The growth of functional endometrial tissue in anatomic sites outside the uterine body. "Infertile patients with or without endometriosis demonstrated reduced HLA-DPA1 and HLA-DPB1 expression in their endometriums." (PMID 40165344, 2025).
hypothyroidism (2 papers, 2020 to 2025). Abnormally low levels of thyroid hormone. "Hypothyroidism has 4 genes (HLA-DPA1, HLA-DQB1, HLA-DQA1, and HLA-DPB1, where two have 5% of predictor variance each and two have 1% each) out of its top 17 genes included among the 641 potentially problematic genes, while 8% is the highest value of predictor variance accounted for by a single gene." (PMID 32694572, 2020).
preeclampsia (2 papers, 2017 to 2024). Preeclampsia is a hypertensive disorder of pregnancy that is characterized by new-onset hypertension with proteinuria presenting after 20 weeks of gestation, and depending on mild or severe forms may initially present with severe headache, visual disturbances, and hyperreflexia. "Placental mRNA expression was examined for the 8 genes enriched in isolated trophoblast side-population cells (CXLC8/IL8, ELL2, GATA6, HK2, HLA-DPB1, INTS6, SERPINE3, UPP1) in placentas obtained from participants with early onset preeclampsia (n = 78) or fetal growth restriction (n = 30)." (PMID 39028417, 2024).
rectal cancer (2 papers, 2023 to 2025). A primary or metastatic malignant neoplasm that affects the rectum. "The HLA-DPB1 gene has been shown to be a good predictive marker of response to nCRT in patients with rectal cancer." (PMID 37895091, 2023).
sarcoma (2 papers, 2019). A usually aggressive malignant neoplasm of the soft tissue or bone. "Expression of HLA-A, HLA-DPB1, and lymphocyte marker LCK were analyzed in TCGA sarcoma subtypes to determine whether a significant loss of antigen presentation in UPS/MFS could limit efficacy of immunotherapies targeting MAGEA3." (PMID 31096717, 2019). "HLA-A mRNA expression and HLA-DPB1 mRNA expression were found to be significantly higher in UPS/MFS compared to other sarcomas, suggesting that efficacy of TCR-based immunotherapies targeting MAGEA3 may not be limited by loss of HLA expression." (PMID 31096717, 2019).
schizophrenia (2 papers, 2012 to 2015). A major psychotic disorder characterized by abnormalities in the perception or expression of reality. "In addition, hsa-mir-219-1 was suggested to play a role in schizophrenia and in N-methyl-D-aspartate (NMDA) glutamate receptor signaling, two pathophysiological mechanisms linked to HLA-DPB1 making our results of valuable information for scientists interested in these pathologies." (PMID 23029284, 2012).
uveitis (2 papers, 2020 to 2024). An inflammatory process affecting a part of or the entire uvea. "This cluster also contained uveitis risk gene HLA-DPB1, which was decreased in JIA-U+ cases (Log2FC = −0.33, P = 0.016) and JIA cases (JIA-U-) compared to controls (Log2FC = −0.34, P = 0.013)." (PMID 33042130, 2020). "Additionally, incorporation of the genetic risk factors serine at position 11 of HLA‐DRB1, rs2523765, and HLA‐DPB1*0201 to this model found that genetic risk factors significantly improve the fit of the statistical model for uveitis." (PMID 39030878, 2024).
Vestibular schwannoma (2 papers, 2022 to 2025). A vestibular schwannoma (also known as acoustic neuroma, acoustic neurinoma, or acoustic neurilemoma) is a benign, usually slow-growing tumor that develops from the VIIIth cranial nerve supplying the inner ear. "Combined with the analysis of data in the GEO database and immunohistochemical verification, it was concluded that HLA-DPB1 and VSIG4 may be candidate biomarkers and potential therapeutic targets for patients with sporadic vestibular schwannoma." (PMID 36304995, 2022).
vitiligo (2 papers, 2019 to 2021). Generalized well circumscribed patches of leukoderma that are generally distributed over symmetric body locations and is due to autoimmune destruction of melanocytes. "By using the Chinese population-specific reference panel, we found three novel independent association signals (rs113465897, rs3130969 and HLA-DPB1*0301) associated with vitiligo within the MHC region in the Han Chinese population." (PMID 35082778, 2021). "In this study, we identified new susceptibility signals associated with risks of vitiligo (rs113465897, rs3130969, HLA-DPB1*0301) and SLE (rs3129898) and confirmed a reported allele, HLA-DQB1*0301, to be associated with SLE." (PMID 35082778, 2021). "Stepwise conditional analysis revealed additional independent signals at rs3130969(p=1.48×10-7, OR=0.69, 95%CI=0.60–0.79), HLA-DPB1*03:01 (p=1.07×10-6, OR=1.94, 95%CI=1.49–2.53) being linked to vitiligo and HLA-DQB1*0301 (P=4.53×10-7, OR=0.62, 95%CI=0.52-0.75) to SLE." (PMID 35082778, 2021). "Using Beagle 4.1, we successfully imputed the SNV, CNV, two–digit and four–digit alleles of HLA genes (HLA-A, HLA-B, HLA-C, HLA-DQA1, HLA-DQB1, HLA-DPA1, HLA-DPB1, HLA-DRB1) and amino acids of 2810 vitiligo subjects (1117 cases, 1693 controls) and 2739 SLE subjects (1,693 controls and 1,046 cases)." (PMID 35082778, 2021).
acoustic neuroma (1 paper, 2022). A type of benign brain tumor that begins in the Schwann cells, which produce the myelin that protects the acoustic nerve - the nerve of hearing. "Based on the results of previous analysis of immune infiltration of VS, we speculate that Immune-related genes VISG4 and HLA-DPB1 may be the targets of acoustic neuroma and verified by immunohistochemistry." (PMID 36304995, 2022).
adrenocortical tumors (1 paper, 2022). "Lower expression of the HLA-DPB1 gene may lead to increased aggressive disease in adult adrenocortical tumors." (PMID 35958927, 2022).
agranulocytosis (1 paper, 2024). "The HLA-DPB1 has been linked to clozapine-induced agranulocytosis." (PMID 38516266, 2024).
alcohol addicts (1 paper, 2024). "Of these, HLA-DPA1 and HLA-DPB1 showed stable expression patterns in alcohol addicts." (PMID 38448893, 2024).
Allergy (1 paper, 2023). An allergy is an immune response or reaction to substances that are usually not harmful. "HLA-B*46:01 (OR = 1.76, 95% CI: 1.08–2.89, p = 0.02) and HLA-DPB1*02:02 (OR = 1.86, 95% CI: 1.03–3.34, p = 0.04) were significantly associated with an increased risk of allergy severity." (PMID 38137494, 2023). "Higher frequencies of HLA-B*46:01, HLA-DPB1*02:02, and HLA-DRB*03:01 were observed in the severe allergy group compared to the mild allergy group." (PMID 38137494, 2023).
anemia (1 paper, 2022). A reduction in the number of red blood cells, the amount of hemoglobin, and/or the volume of packed red blood cells. "In this study, a significant correlation was found between HLA-DRB3*01:01 and thrombocytopenia, HLA-DPB1*04:02 and leukopenia, and anemia in ICI treatment." (PMID 36177028, 2022).
Chagas disease (1 paper, 2017). A parasitic infection caused by Trypanosoma cruzi. "Some of these differentially expressed genes were previously associated to Chagas disease (eg, IL7, CCR7, CCL19, GATA4, HLA-DPB1)." (PMID 28575239, 2017).
chondrosarcoma (1 paper, 2024). A malignant cartilaginous matrix-producing mesenchymal neoplasm arising from the bone and soft tissue. "Here, we observed a gCAF subcluster (CD68, HLA-DPB1, and CFD) in conventional central chondrosarcoma, which was characterised by granulocyte activation." (PMID 38267611, 2024).
dengue (1 paper, 2020). "This study analyzed the rs8099917 of IFNL3, rs2267966 of CD27, and rs9277534 of HLA-DPB1 for their association with dengue severity in a Thai population." (PMID 33308178, 2020). "To identify genes associated with dengue severity that have not been studied yet, we performed genetic association analyses of interferon lambda 3 (IFNL3), CD27, and human leukocyte antigen-DPB1 (HLA-DPB1) genes in Thai dengue patients." (PMID 33308178, 2020). "To obtain complete knowledge of genes/markers that predict dengue outcomes, we investigated genes that have not been studied to date, interferon lambda 3 (IFNL3), CD27, and human leukocyte antigen-DPB1 (HLA-DPB1)." (PMID 33308178, 2020).
depression (1 paper, 2019). "Unlike the associations of HLA-DPB1 with ASD and ID, the gene-based tests for HLA-B with ADHD or depression are not significant." (PMID 30976114, 2019).
endometrial cancer (1 paper, 2020). Primary or metastatic malignant neoplasm involving the endometrium (mucous membrane that lines the endometrial cavity). "Our results identified CD74, HLA-DRB5, CD52, HLA-DPB1 and HLA-DRB1 as possible valuable genetic markers for the diagnosis and prognosis of endometrial cancer and provided a theoretical basis for immunotherapy targets for its clinical treatment." (PMID 33159014, 2020).
epilepsy (1 paper, 2022). A brain disorder characterized by episodes of abnormally increased neuronal discharge resulting in transient episodes of sensory or motor neurological dysfunction, or psychic dysfunction. "Although epilepsy is not considered a primary immune-mediated disease, DRE microglial clusters 7, 5, 9 and 11 were characterized by high gene expression levels of TNF, HLA-DRA and HLA-DPB1 and low CX3CR1 and P2RY12 gene expression levels." (PMID 35739273, 2022).
goiter (1 paper, 2017). Enlargement of the thyroid gland usually caused by lack of iodine in the diet, hyperthyroidism, or thyroid nodules. "In the present case, HLA-DPB1*05:01 homozygosity might have been involved in the development of his GD, and this may have manifested as a full-blown goiter and long-standing severe hyperthyroidism despite the rapid negative conversion of TBII assay results." (PMID 28162094, 2017).
Granuloma (1 paper, 2025). A compact, organized collection of mature mononuclear phagocytes, which may be but is not necessarily accompanied by accessory features such as necrosis. "However, our study presents new evidence for the expression of HLA-DPB1 and HLA-DQA1 in macrophages within CS granulomas." (PMID 40521183, 2025).
juvenile idiopathic arthritis (1 paper, 2014). Juvenile idiopathic arthritis (JIA) is the term used to describe a group of inflammatory articular disorders of unknown cause that begin before the age of 16 and last over 6 weeks. "A bulk of the difference between them lies in a 19 aa region that includes a 6 aa stretch that has been hypothesized to mimic self HLA-DPB1*0201, thereby being involved in T-cell reactivity to self in patients with juvenile idiopathic arthritis." (PMID 24945689, 2014).
leiomyosarcoma (1 paper, 2019). An uncommon, aggressive malignant smooth muscle neoplasm, usually occurring in post-menopausal women. "Given the prior use of HLA-DPB1-restricted MAGE-A3-specific CD4+ T cells, we analyzed mRNA expression of HLA-DPB1 and found that expression was significantly higher in UPS/MFS compare to leiomyosarcoma (p < 0.01) and synovial sarcoma (p < 0.001)." (PMID 31096717, 2019).
liver failure (1 paper, 2023). A liver disease characterized by the liver losing or has lost all of its function. "Nevertheless, HLA-DPB1*05:01:01 was marginally associated with an increased risk of liver transplantation or death from liver failure." (PMID 37325616, 2023).
liver fibrosis (1 paper, 2022). "In our study, we found that HLA-DPA1 and HLA-DPB1 differed significantly in groups with different degrees of liver fibrosis." (PMID 36406135, 2022).
lung adenocarcinoma (1 paper, 2025). A carcinoma that arises from the lung and is characterized by the presence of malignant glandular epithelial cells. "In lung adenocarcinoma, high expression of CCL20, IL23A, MMP1 and MMP3 was significantly associated with poor patient prognosis, whereas high expression of FOS, HLA-DPA1, HLA-DPB1, HLA-DQA1, HLA-DQB1 and HLA-DRA was significantly associated with improved patient prognosis." (PMID 40016789, 2025).
lymphoproliferative disorders (1 paper, 2024). "Using SSP genotyping, we evaluated HLA class I (HLA-A/B/C) and class II (HLA-DPB1/DQB1/DRB1) genes with the purpose of finding possible statistical connections between these genes and lymphoproliferative disorders." (PMID 38535155, 2024).
metastatic cancer (1 paper, 2023). A carcinoma which has spread from the original site of growth to another anatomic site. "Moreover, adoptive CD4+ T cell therapy using HLA-DPB1*0401 restricted TCR recognizing MAGEA3 has been proved to be effective in 17 patients with metastatic cancer and 4/17 patients treated with DPB1*0401 restricted TCR-T cells showed durable clinical response (1CR, 3PR)." (PMID 37287989, 2023).
mixed cellularity Hodgkin lymphoma (1 paper, 2017). "Additionally, independent loci within the HLA region are observed for nodular sclerosis Hodgkin lymphoma (rs9269081, HLA-DPB1*03:01, Val86 in HLA-DRB1) and mixed cellularity Hodgkin lymphoma (rs1633096, rs13196329, Val86 in HLA-DRB1)." (PMID 29196614, 2017).
neuromyelitis optica (1 paper, 2014). A rare inflammatory disease of the central nervous system characterized mainly by attacks of uni- or bilateral optic neuritis (ON) and acute myelitis. "Recently, we reported that HLA-DRB1*0405 and HLA-DPB1*0301 are susceptibility alleles, while DRB1*0901 and DPB1*0401 are protective alleles for Japanese MS when neuromyelitis optica (NMO) and NMO spectrum disorder (NMOSD) patients are excluded." (PMID 24736746, 2014).
ophthalmoplegia (1 paper, 2022). Weakness or paralysis of at least one of the muscles controlling the movement of the eye. "Preliminary results suggest that “low expression” HLA-DPB1*105:01 genotypes, which were also more common in African controls compared to European controls, associated with African juveniles with treatment-resistant ophthalmoplegia." (PMID 35280301, 2022).
optic neuritis (1 paper, 2021). Optic neuritis is inflammation of the optic nerve, the nerve that carries the visual signal from the eye to the brain.The conditionmay cause sudden, reduced vision in the affected eye(s). "For NMOSD, old age at onset, long disease duration and many relapses were risk factors for high EDSS scores, but episodes of bilateral optic neuritis, experience of LESCL and harbouring the HLA-DPB1*05:01 allele were not." (PMID 33436735, 2021).
Oral ulcer (1 paper, 2022). Erosion of the mucous mebrane of the mouth with local excavation of the surface, resulting from the sloughing of inflammatory necrotic tissue. "Among them, the expression of inflammation-related genes such as CCRL2, HLA-C, GSDMB, HLA-DPB1, and MAPT increased in patients with oral ulcers." (PMID 35958581, 2022).